MPO (myeloperoxidase)
Diseases named in the same sentence as MPO in open-access papers (continued):
Sharing a sentence is not in itself a finding about the gene and the disease.
COVID-19 (continued). "Indeed, persistent neutrophil accumulation and the release of neutrophil extracellular traps (NETs) carrying NE and myeloperoxidase in the lower respiratory tracts of severely ill COVID-19 patients are associated with acute alveolar injury." (PMID 38397474, 2024). "Here, we investigate whether myeloperoxidase, an antimicrobial released by neutrophils, is associated with EG damage in COVID-19 patients." (PMID 37147421, 2023). "As expected, the levels of monocyte and neutrophil inflammation markers (soluble CD14 (sCD14) and myeloperoxidase (MPO)) were increased in the severe group compared with mild and control groups, alluding to the association between microbial translocation and COVID-19 severity." (PMID 37205106, 2023). "MPO has also been associated with worse clinical outcomes in COVID-19 patients." (PMID 37908356, 2023). "Interestingly, despite clinical recovery, MPO levels and MPO activity remained elevated in the severe COVID19 group, and upregulated neutrophils-associated immune signatures including MPO levels was associated with a pulmonary sequela of COVID-1924." (PMID 37147421, 2023). "The immunoblotting results revealed that the levels of COVID-19 EV-induced NETs-associated proteins [e.g., myeloperoxidase (MPO), peptidylarginine deiminases 4 (PAD4), and citrullinated histone H3 (citH3)] were inhibited completely in TLR8 knockdown cells, which was consistent with IFA data." (PMID 37904132, 2023). "Our results suggest myeloperoxidase is associated with EG damage and severe COVID-19." (PMID 37147421, 2023). "Research shows that infiltrating neutrophils, a hallmark of COVID-19, can release myeloperoxidase (MPO), which can activate several pathways that lead to elevated cytokines and production of ROS such as hypochlorous acid (HOCl), superoxide (O2•-), and hydrogen peroxide (H2O2)." (PMID 37261353, 2023). "To assess the extent of granulocyte activation and its association with LDG subset frequencies during acute COVID-19, we measured the circulating NETs, in the form of MPO-DNA complexes, together with calprotectin and MPO as additional markers of granulocyte activation in the patients’ sera." (PMID 34228753, 2021). "Considering that MPO, apelin, and myostatin showed consistent alteration patterns upon COVID-19, which is in line with their previously identified regulatory roles, we next explored the potential association between MPO, apelin, and myostatin and metabolic parameters." (PMID 34916489, 2021). "In line with this, COVID-19 sera were found to contain abundant NETosis markers such as cell-free DNA, myeloperoxidase- (MPO-) associated DNA, and citrullinated histone H3 (citH3), together with elevated levels of the acute-phase C-reactive protein (CRP) and D-dimer." (PMID 34367376, 2021). "Finally, a focused 2024 review on MPO emphasized its role as a central effector of oxidative tissue injury across diseases (including lung injury/COVID), lending mechanistic support to the GWAS-inferred causal role of MPO pathways in severe COVID-19." (PMID 41209585, 2025). "Furthermore, infiltrating neutrophils, a hallmark of COVID-19, can release myeloperoxidase (MPO), which can activate several pathways that lead to elevated cytokines and production of ROS such as hypochlorous acid (HOCl), superoxide (O2•-), and hydrogen peroxide (H2O2) 22-24." (PMID 33390833, 2021). "According to previous reports, the levels of NET-specific markers, such as free DNA and MPO, in patients with coronavirus disease 2019 (COVID-19) are closely related to the number of neutrophils." (PMID 40597301, 2025). "The results from this study underscore the critical role of various biomarkers, particularly anti-MPO, in predicting inflammation and related conditions in COVID-19 patients." (PMID 41239211, 2025). "LHN treatment in severe COVID-19 patient-derived samples exhibited a marked reduction in NET-associated markers, such as cfDNA, MPO and NE activity." (PMID 39894864, 2025).
COVID-19 (continued). "Significantly higher amounts of NET remnants were detected in COVID-19 sera as compared to controls by anti-MPO (p < 0.0001), anti-alpha enolase (p = 0.0007) and anti-calprotectin (p = 0.0009)." (PMID 40076841, 2025). "Regarding the mediators related to neutrophilic activity, MMP8, lactoferrin, lipocalin-2, and MPO (all proteins potentially released by activated neutrophils) were augmented in the serum at all timepoints during COVID-19." (PMID 40710346, 2025). "And all specific for NETs remnants, histone-DNA, MPO-DNA, and NE-DNA complexes displayed similar profiles in COVID-19 patients and healthy controls." (PMID 41309368, 2025). "In another study, elevated levels of kinin peptides and MPO–DNA complexes (considered as NET markers) in the blood of patients with COVID-19 were shown." (PMID 39996829, 2025). "Elevated concentrations of tissue pKa, BK, and myeloperoxidase complexes with DNA (MPO–DNA) were also recorded in the blood of patients with COVID-19." (PMID 39996829, 2025). "MPO levels, activity, and soluble endothelial glycocalyx levels are significantly elevated in patients with COVID-19, increasing proportionally to disease severity." (PMID 40241896, 2025). "Middleton and colleagues identified increased levels of MPO-DNA complexes in patients with COVID-19 and correlated directly and strongly with the severity of illness." (PMID 39179952, 2025). "Additional studies have revealed that plasma from patients with severe COVID-19 has increased levels of Cit-H3 and myeloperoxidase-DNA (MPO-DNA) in comparison to patients with classical ARDS." (PMID 40801583, 2025). "NET remnants were quantified by assays using anti-MPO, anti-enolase and anti-calprotectin antibodies in 25 healthy subjects and 40 COVID-19 sera." (PMID 40076841, 2025). "The study elucidates that although autoantibody (anti-MPO) levels remained within normal range, their significant association with neutrophilic inflammation (NLR) and coagulation (PTT) suggests a role in COVID-19 thromboinflammation." (PMID 41239211, 2025). "MPO has been found to be significantly elevated in the plasma of COVID-19 patients compared to healthy controls." (PMID 39599792, 2024). "The MCI indicators of succinate dehydrogenase, cationic proteins, and myeloperoxidase in pregnant women with COVID-19 were reduced in relation to the control group (p < 0.0001)." (PMID 38392189, 2024). "The colocalization analysis supported the association between all potential causal protein-outcome pairs identified in the MR analysis except for MPO with hospitalized COVID-19 which was subsequently excluded." (PMID 40303168, 2024). "The COVID-19 group had higher CitH3 (28.29 vs 20.29 pg/mL, p = 0.022), and cfDNA, MPO-DNA, and NE-DNA (7.87 vs 2.56 ng/mL; 0.80 vs 0.52 and 1.04 vs 0.72, respectively, p < 0.001 for all) than the controls throughout hospitalisation." (PMID 38243237, 2024). "Elevated levels of NET parameters, such as cell-free DNA, MPO-DNA complexes, and citrullinated histone H3, were detected in the blood serum of COVID-19 patients." (PMID 39742024, 2024). "Several studies have measured NET markers in the blood of patients with COVID-19, and overall, our results corroborated previous findings that COVID-19 patients have significantly elevated levels of NETs, including MPO and citH3." (PMID 39599792, 2024). "Potential mechanisms for dapsone’s efficacy in COVID-19 include decreasing inflammation via the inhibition of myeloperoxidase, inhibiting neutrophil tissue destruction, and acting as an NLPP3 inflammasome inhibitor." (PMID 38792737, 2024). "Increased levels of MPO generated more HOCl, affecting NO synthase and contributing to COVID-19-induced dysfunctions, such as vascular inflammation and platelet aggregation." (PMID 38275657, 2024).
COVID-19 (continued). "FAS (OR [95% CI] = 0.98 [0.97, 1.00], p = 4.56 ×10-2, proportion = 8.0%) and MPO (OR [95% CI] = 0.98 [0.97, 1.00], p = 2.13 ×10-2, proportion = 8.1%) partially mediated the causal effect between LTL and COVID-19 severity." (PMID 38882679, 2024). "Recent studies have shown a correlation between COVID-19 and MPO, the major particle-resident protein of NETs." (PMID 38275657, 2024). "Activated leukocytes, such as neutrophils, release antimicrobial agents like myeloperoxidase (MPO), which has been shown to correlate with syndecan-1 shedding in COVID-19." (PMID 38753622, 2024). "The researchers found MPO levels were not only increased in the samples of COVID-19 patients in comparison with healthy individuals but also in those of severe COVID-19 patients compared with asymptomatic COVID-19 patients." (PMID 38275657, 2024). "SARS-CoV-2 can activate neutrophils to release myeloperoxidase (MPO), a leukocyte heme-enzyme, and increased peripheral MPO levels were observed in COVID-19 ICU patients." (PMID 37147421, 2023). "The staining intensity of the oxidized DNA marker (8-OHdG) was significantly higher in COVID-19 patients compared to control lung tissue and showed a positive correlation with the MPO." (PMID 36768969, 2023). "The strength of this study is that we used pre-vaccinated samples, reducing potential vaccine-induced confounders, and we determined the functional activity of MPO in COVID-19 subjects compared to previous studies that reported only quantitative levels." (PMID 37147421, 2023). "Patients with severe COVID-19 have been shown to present elevated levels of circulating histones and myeloperoxidase DNA (MPO-DNA) which are two specific markers of NETs." (PMID 37240292, 2023). "The serum from COVID-19 patients shows the presence of DNA, histones (Cit-H3), and myeloperoxidase (MPO-DNA) which are specific components for NETs that release inflammatory cytokines such as IL-1β, and IL-6." (PMID 37374090, 2023). "The findings of the prospective cohort study indicate a significant increase in CitH3 and MPO in COVID-19 patients who require endotracheal intubation." (PMID 38283037, 2023). "defined a population of ‘developing neutrophils’ in subjects with COVID-19 that seemed to derive from plasmablasts and overlap in marker expression with immature neutrophils (i.e., MPO, ELANE)." (PMID 38022639, 2023). "We observed higher levels of NETosis markers, i.e., MPO and MPO/DNA complexes, in COVID-19 patients overall, which is in line with previous research." (PMID 37239041, 2023). "The other DEG is MPO, a gene that codes for myeloperoxidase, a leukocyte-derived enzyme whose plasmatic levels are elevated in mild to severe cases of COVID-19 and down-regulated in patients with very severe disease." (PMID 36650374, 2023). "The concentration of NETs, measured as MPO-DNA complexes, was shown to be augmented in plasma, tracheal aspirate, and lung autopsies tissues from COVID-19 patients." (PMID 37762464, 2023). "Further research is needed to evaluate the utility of MPO inhibitors as potential therapeutics against severe COVID-19." (PMID 37147421, 2023). "S100A8, MMP-8 and MPO are involved in lung pathology as consequences of lung tissue degradation in tuberculosis, emphysema, COVID-19 or COPD." (PMID 37375484, 2023). "Sera from COVID-19 patients revealed increased levels of extracellular DNA and MPO-DNA and citrullinated histone H3, specific markers of NET." (PMID 37673862, 2023). "Although the link between MPO and severe disease is complex, it is likely that increased MPO levels and activity promote inflammation contributing to COVID-19 pathology." (PMID 37147421, 2023). "The frequency of MPO-positive neutrophils was reduced in the COVID-19 female vs. the male patients and appeared to be sporadically under the influence of estradiol." (PMID 37896963, 2023). "A significant increase in both NE-DNA and MPO-DNA complexes levels was observed in COVID-19 ICU patients (p < 0.0001) compared to HCs." (PMID 37248708, 2023).
COVID-19 (continued). "A recent study evaluated the specific parameters of NETs on 91 hospitalized patients with COVID-19 including cf-DNA, MPO-DNA, and NE-DNA complexes and citrullinated Histone 3 (citH3)." (PMID 37869674, 2023). "Following the formation of NETosis in patients with COVID-19, citrullinated histone H3 (Cit-H3), cell-free DNA (cfDNA), and myeloperoxidase (MPO)-DNA levels are increased, inducing multi-organ damage and death from severe SARS-CoV-2 infection." (PMID 37654571, 2023). "At acute and convalescent phases, plasma MPO activity were significantly higher in COVID-19 subjects compared with controls [controls, median (IQR); 36.99 (34.80–39.01) unit/ml, acute (p < 0.01); convalescent (p < 0.001)]." (PMID 37147421, 2023). "Plasma MPO-DNA complexes increased in COVID-19 patients and illness severity correlated directly with plasma MPO-DNA complexes." (PMID 36983067, 2023). "The levels of both extracellular DNA and MPO-DNA were much higher in patients on mechanical ventilation compared to regular COVID-19 patients." (PMID 37673862, 2023). "In COVID-19 plasma, MPO levels, MPO activity and levels of soluble EG proteins are significantly raised compared to controls, and concentrations increase in proportion to disease severity." (PMID 37147421, 2023). "The difference in NETs was more obvious when examined using the anti-MPO antibody and was more consistent in the male patients with COVID-19 during DHT treatment." (PMID 37896963, 2023). "The sera of patients with COVID-19 have elevated levels of cell-free DNA, myeloperoxidase-DNA (MPO-DNA), and citrullinated histone H3 (Cit-H3); the latter two are specific markers of NETs." (PMID 37189799, 2023). "Neutrophil migration and infiltration are usually assessed by myeloperoxidase (MPO) assays and associated with NET formation, one of the features of ALI/ARDS in COVID-19 patients." (PMID 37090710, 2023). "At acute and convalescent phases, COVID-19 subjects had significantly higher plasma MPO levels compared with controls [controls, median (IQR); 5.74 (5.51–11.61) ng/ml], both time points (p < 0.01)." (PMID 37147421, 2023). "We confirmed elevated plasma levels of NET markers (MPO and histone H3) in our COVID-19 patients on hospital admission." (PMID 37896963, 2023). "Further studies to evaluate the utility of MPO inhibitors as a therapy against severe COVID-19 are warranted." (PMID 37147421, 2023). "In this cohort of COVID-19 plasma (n = 25), we observed positive correlations between MPO levels and syndencan-1 shedding at both acute (R = 0.42, p = 0.03) and convalescent (R = 0.39, p = 0.052) phases." (PMID 37147421, 2023). "We visualized NETs based on the expression of histone H3 and MPO evaluated by immunohistochemistry in patients with COVID-19." (PMID 37896963, 2023). "The MPO levels were increased in neutrophils from the male patients with COVID-19 and stimulated by DHT, while markers of NETs were more abundant in the plasma from the COVID-19 and post-COVID-19 patients." (PMID 37896963, 2023). "Finally, recent research suggests that severe hypouricemia can cause endothelial dysfunction, lower blood pressure, reduce myeloperoxidase activity and promote lipid peroxidation in healthy individuals, which could worsen the outcome of COVID-19 patients with low uric acid levels." (PMID 38051999, 2023). "The levels of MPO activity and circulating cell-free DNA were generally increased in patients with COVID-19." (PMID 37896963, 2023). "The markers of NETs formation, such as circulating DNA, nucleosomes, citrullinated histones, neutrophil elastase activity or myeloperoxidase-DNA complexes were found in sera of COVID-19 patients at a higher level as compared to healthy donors." (PMID 36902325, 2023). "In COVID-19 patients, we observed increased plasma MPO levels, MPO activity, syndecan-1 and glypican-1 concentrations to be associated with severe disease." (PMID 37147421, 2023).
COVID-19 (continued). "A recent report also showed that cell cfDNA and NET markers such as citrullinated histone H3 and MPO-DNA complexes were elevated in COVID-19." (PMID 36008932, 2022). "We confirm biochemically and morphologically that neutrophils from patients with COVID-19 generate MPO-positive NETs in response to PMA and LPS and that fewer NETs are visualised in the presence of ruboxistaurin." (PMID 35382002, 2022). "Plasma levels of MPO-DNA complexes and H3Cit correlated with COVID-19 not only with thrombotic events but also with disease severity." (PMID 36466841, 2022). "Nevertheless, the ratio of Nu.Cit-H3R8, Cit-H3, NE and MPO levels on neutrophils were similar between the two cohorts, suggesting a similar NETs’ formation potential in critical COVID-19 and septic shock patients admitted to ICU." (PMID 36008932, 2022). "MPO/DNA complexes and H3Cit plasma levels were elevated in COVID-19 patients compared to healthy controls." (PMID 33982161, 2022). "Transcriptomic analysis of immature neutrophils in severe COVID-19 reveals higher expression of genes involved in neutrophil extracellular trap (NET) formation, such as MPO, ELANE, PRTN3, and genes associated with a poor outcome in sepsis." (PMID 35401519, 2022). "Myeloperoxidase (MPO), a mediator of inflammation and oxidative stress, was found to be several-fold upregulated in the lungs and whole blood of COVID-19 patients." (PMID 35159254, 2022). "Another study characterized the interaction between COVID-19 and C5aR1, where MPO-DNA complex levels were found to correlate with thrombin/antithrombin (TAT) activity, suggesting activation of the thrombin axis." (PMID 35409152, 2022). "Together, these data suggest that neutrophils from acute-phase COVID-19 patients are in a state of exhaustion, resulting in reduced production of ROS, MPO and classical NETs release upon secondary bacterial challenge." (PMID 35007290, 2022). "Immunostaining of lung, kidney, and heart tissues of COVID-19 patients revealed positive staining of H3Cit, MPO-DNA, NE, and DNA." (PMID 36224604, 2022). "Particularly, H3Cit, MPO, MPO-DNA, NE, nucleosomes, and DNA, which are deemed as NETs biomarkers, have been evaluated in VTE, CAD, IS, cancer-associated thromboembolism, and COVID-19 associated thromboembolism." (PMID 36224604, 2022). "During the initial stage of the COVID-19 pandemic, serum markers of NETs – myeloperoxidase (MPO)-DNA, and citrullinated histone H3 (Cit-H3) – were first reported to be elevated in the serum of COVID-19 patients." (PMID 36069182, 2022). "The number of neutrophils (MPO+ cells) was significantly higher in thrombi of COVID-19 patients than controls (respectively, median MPO+ cells/mm2 = 2110, [IQR 1754–2580] vs. 1333, [IQR 1060–2082], p = 0.04)." (PMID 35105380, 2022). "Like a number of other authors, we have here confirmed that NE, MPO, and cirDNA concentrations in the plasma of patients with severe COVID-19 are significantly higher than in a large cohort of healthy individuals." (PMID 36443816, 2022). "A significantly higher amount of neutrophil extracellular traps [and related markers such as cell-free DNA and myeloperoxidase-DNA (MPO-DNA)] was found when compared with non-COVID-19 thrombi." (PMID 35360017, 2022). "Among protein biomarkers, Ang-2, ET-1, sICAM-1, sVCAM-1, sE-selectin, sTREM-1, IL-6, IL-8, and MPO levels differed according to COVID-19 severity." (PMID 35453080, 2022). "Sera from patients with COVID-19, exhibited elevated levels of MPO-DNA, cfDNA, and citrullinated histone H3, with cfDNA and MPO-DNA being even higher in patients receiving mechanical ventilation compared to non-ventilated hospitalized patients." (PMID 35741047, 2022). "Cell-free DNA, MPO/DNA complexes and H3Cit were shown to be increased in sera from 50 hospitalized patients with COVID-19 in comparison to 30 healthy controls." (PMID 33982161, 2022).